ALB (albumin)
Diseases named in the same sentence as ALB in open-access papers (continued):
Sharing a sentence is not in itself a finding about the gene and the disease.
Obesity (continued). "Individuals who transited to dynapenia were tended to be older and had a higher obesity profile (BMI, WC, fat mass, body fat percentage, and FMR) as well as a lower albumin level." (PMID 35571885, 2022). "Evans Blue-albumin leaking into the heart was significantly higher in WT mice than NEKO mice, further supporting the role of NE in obesity-related vascular leakage." (PMID 35892585, 2022). "In the BC subnetwork, the targets with the top three BC values were albumin (ALB), interleukin-6 (IL6), and AKT serine/threonine kinase 1 (AKT1), which were considered the core targets connected with microbes to alleviate obesity." (PMID 36139478, 2022). "Compared with the underweight group, HGB, HCT, TC, TG, LDL-c, Scr, ALB, ALT, and HBA1c increased significantly in the obesity group, whereas the opposite results were found in the HDL-c, FIB, and NIHSS scores." (PMID 36578955, 2022). "In comparing tertile 3 with tertile 1, 21.05%, 26.67%, 24.53%, and 24.04% of the total effects of dietary fiber on albumin, globulin, total bilirubin, and GGT were mediated by obesity, respectively." (PMID 36684870, 2022). "This is generally due to the chronic pro-inflammatory state of patients with obesity, which results in an increase in acute-phase proteins such as CRP, as well as a decrease in albumin concentrations, both of which are clinical markers of inflammation." (PMID 35010957, 2021). "C-peptide, insulin, glucose, HbA1c, uric acid, fibrinogen, free triiodothyronine, albumin, gamma glutamyl transferase (GGT), and alkaline phosphatase are the top ten ranked biomarkers for obesity (based on p-value)." (PMID 33138081, 2020). "Although higher BMI was observed in this group, lower albumin levels highlight the so-called ‘obesity paradox,’ underscoring that body weight alone is not a reliable marker of nutritional adequacy." (PMID 41295296, 2025). "The albumin‐to‐creatinine ratio (ACR) is widely used to estimate urinary albumin excretion, but in individuals with high fat‐free mass (FFM), such as those with obesity, elevated urinary creatinine may lead to underestimation of albuminuria." (PMID 40557880, 2025). "Social frailty was found to be correlated with poor nutritional status as measured by MNA, low serum albumin levels, no consumption of breakfast, overweight or obesity as measured by BMI, and central obesity as determined by waist circumference." (PMID 40573130, 2025). "Among patients at BMI extremes (i.e., with underweight or class 3 obesity), however, CV morbidity—rather than general demographics and non-CV conditions—was related to serum albumin status, demonstrating a higher frequency in hypoalbuminemic individuals." (PMID 39728268, 2024). "Furthermore, the serum albumin and the expression of CYP3A4 decrease with obesity, whereas the expression of UGT1A1 increases." (PMID 38309958, 2024). "In patients with obesity, a prominent positive correlation (r=0.56, p=0.00468) was revealed between the CPT value of the median nerve at stimulating frequency of 2000 Hz and the albumin/creatinine ratio (ACR)." (PMID 39081789, 2024). "Inflammation may have a triple effect on LDL in obesity: it enhances the expression of Lp-PLA2 and secretory PLA2; it decreases the albumin’s ability to sequester NEFA; and it increases the oxidative stress." (PMID 37777014, 2023). "Our findings revealed that adding a high-fat diet to obesity caused a non-significant change in serum levels of ALT, ALP, total and direct bilirubin, and albumin concentration, but a substantial rise in AST when compared to the control." (PMID 36995465, 2023). "The results indicate that albumin’s FFA transport function may be involved in the development of hepatic lipid accumulation and dysregulated glucose metabolism in obesity." (PMID 37432201, 2023).
Obesity (continued). "While we matched several important variables in the study, the NIS database does not contain granular data such as serum albumin levels to match other important variables and assess the true contribution of obesity to outcomes in patients undergoing BKAs." (PMID 36615067, 2022). "Overall, the demographic covariates including body weight, body mass index, BSA, age, gender, obesity, albumin, and markers of hepatic and kidney functions, had no meaningful impact on the PK of TQ-B3101 and TQ-B3101M." (PMID 35115931, 2021). "In addition, this study demonstrated that serum MaR1 concentrations were positively correlated with AST/ALT, ALB, A/G, and HDL-C and negatively correlated with age, obesity, FBG, ALT, GGT, UA, and TG." (PMID 34461919, 2021). "The study aimed to evaluate the albumin-to-creatinine ratio (ACR), urinary alpha-1-acid glycoprotein (α1-AGP), and mRNA of podocyte-specific proteins as indicators of glomerular injury and their relationship with the degree of obesity and metabolic disorders." (PMID 34575240, 2021). "Since increased BMI (or obesity) is unlikely to affect the binding of posaconazole to albumin, the free fraction is expected to remain unaffected, and thus, a decrease in total concentration will subsequently result in a lower unbound concentration." (PMID 31171022, 2019). "Hazard ratios and 95% confidence intervals for prediabetes development according to percent changes in serum albumin level in subjects without obesity or insulin resistance." (PMID 28430803, 2017). "Although plasma proteins such as a1 acid-glycoprotein and lipoproteins are highly concentrated in obesity, binding of drugs to albumin does not seem to be altered." (PMID 24883145, 2014). "The present study investigated if differences exist in myotubes from individuals with (OB) or without (LN) obesity incubated in control (bovine serum albumin [BSA]) or obesogenic (Ob) medium, at baseline or in response to cardiotoxin (CTX)-induced damage and recovery." (PMID 41493388, 2026). "Similarly, in vivo experiments have demonstrated that BAM15@BSA NPs, a functionalized drug-albumin nanocomposite prepared by co-assembling BAM15 with bovine serum albumin, exhibit a remarkable ability to target the liver, leading to potent anti-obesity effects." (PMID 37900126, 2023). "Moreover, the richness of the data collected allowed us to identify an association between various micronutrients and prognosis, which is truly independent of many confounding factors such as age, sex, albumin or obesity." (PMID 36986247, 2023). "In a pooled analysis of PK data from adult patients using a population approach, demographic covariates including body weight, body mass index, BSA, age, gender, obesity, albumin, and markers of hepatic and kidney functions, had no meaningful impact on the PK of TQ-B3101 and its active metabolite." (PMID 35115931, 2021). "Nonwhite race, obesity, the elevated levels of serum bicarbonate, creatinine, total calcium, vitamin B12, urinary albumin and iodine may be protective factors of lupus." (PMID 32537455, 2020). "In fact, severe obesity compared with milder obesity status could not predict the occurrence of increased urinary albumin excretion." (PMID 26060835, 2015). "Indeed, specific deletion of CB1R in RPTC (RPTC-CB1R-/-) did not prevent obesity in mice, but significantly reduced the obesity-induced lipid accumulation in the kidney as well as renal dysfunction, urinary albumin-to-creatinine ratio (ACR), inflammation, and renal fibrosis." (PMID 34305821, 2021). "Thus, the serum albumin expressed in the brain of DIO rats but not DR rats might be a factor leading to obesity and obesity resistance." (PMID 29937895, 2017).
Obesity (continued). "Other possible reasons for heterogeneity were that low albumin was not the only susceptibility factor for SSI, obesity, age, low total lymphocyte counts, transferrin and combinations of these factors could all exerted an impact on SSI, and there were inconsistent factors among these studies." (PMID 28093079, 2017). "Haematocrit, serum albumin, and AGP showed no specific trend with age, which concurs with other simulations of paediatric obesity populations and agrees with various publications that report data for paediatrics with and without obesity." (PMID 38675150, 2024). "In obesity, AMPK activity remains unaltered by FFA-albumin overload, but its activity failed to decrease the hyperactivation of the mTORC1 signal, which leads to the obesity-mediated exacerbation of proteinuria-induced tubulointerstitial damage." (PMID 33121167, 2020). "Thus, in this study we sought to determine whether children with overweight/obesity and NAFLD show signs of renal functional alterations, as assessed by eGFR and urinary albumin excretion, compared to children with overweight/obesity but without NAFLD as well as to healthy normal-weight controls." (PMID 27472326, 2016). "However, for both male and female children, the ALB and FT3 levels were not different between the two groups (p > 0.05), whereas the ALP level was significantly higher in male patients with obesity and NAFLD than in male children with obesity alone (p > 0.01)." (PMID 37720532, 2023).
nephrotic syndrome (325 papers, 2008 to 2026). A collection of symptoms that include severe edema, proteinuria, and hypoalbuminemia; it is indicative of renal dysfunction. "Further workup revealed nephrotic syndrome, with proteinuria of 6.5g/day, and serum Albumin 26 g/L, associated with anti-PLA2R of 223 RU/ml." (PMID 39792734, 2025). "The study included 26 patients with PLA2Rab-associated MN, a median age of 57 years, nephrotic syndrome (proteinuria 7.1 g/day, serum albumin 18 g/L), and preserved kidney function." (PMID 40003652, 2025). "The patient presented with features of high-risk nephrotic syndrome, including a urinary protein quantification of 8.28 g/24 h and serum albumin level of 29 g/L." (PMID 41030252, 2025). "The study included 30 patients with PLA2Rab-associated MN, median age 45 years, nephrotic syndrome (proteinuria 11 g/day, serum albumin 20.4 g/L), and preserved kidney function (eGFR 80 mL/min/1.73 m2)." (PMID 40003652, 2025). "The administration of albumin and metoprolol greatly benefited in managing the fluid and electrolyte loss associated with nephrotic syndrome." (PMID 40909076, 2025). "Lower serum Albumin levels in MM patients are associated with clinical factors like kidney disease or nephrotic syndrome, which reflects the severity of this disease." (PMID 39329904, 2024). "Serum albumin level, hematuria and residence were factors associated with infection in nephrotic syndrome." (PMID 38987746, 2024). "In our pedigree study, all three probands met the diagnostic criteria for the nephrotic syndrome: albumin levels less than 30 g/L, 24-h urine protein levels more than 3.5 g/L, edema, and/or high lipid levels." (PMID 39184349, 2024). "The expression of this ASIC2b variant was detected only in rats with nephrotic syndrome and was due to albumin endocytosis and the activation of the ERK-signaling pathway in all cell types that form CCDs except type A intercalated cells." (PMID 38540182, 2024). "It was also supported by Indian research, which indicated that a serum albumin level < 1.5 g/dl was an independent risk factor for infection in children with nephrotic syndrome." (PMID 38987746, 2024). "Nephrotic syndrome in adults is defined as nephrotic-range (≥3.5g/24h) proteinuria with low serum albumin, usually associated with edema, hyperlipidemia, and lipiduria." (PMID 39131015, 2024). "Patients with nephrotic syndrome are at increased risk of venous thromboembolism, especially if albumin drops below 2.5 g/dL." (PMID 38610755, 2024). "Studies identified that decreased levels of serum albumin and immunoglobulin were the independent risk factors or infection in children with nephrotic syndrome." (PMID 38987746, 2024). "In this study, serum albumin level was associated factor of infection in children with nephrotic syndrome." (PMID 38987746, 2024). "In this study, we identified serum albumin level, hematuria, and residence as factors associated with infection in children with nephrotic syndrome." (PMID 38987746, 2024). "In comparison, common causes of a low albumin gradient (SAAG less than 1.1 g/dL) include nephrotic syndrome, serositis, pancreatitis, peritoneal tuberculosis, and peritoneal carcinomatosis." (PMID 38899262, 2024). "Loss of albumin (the main antioxidant molecule) in urine and almost complete oxidation of serum albumin in patients with nephrotic syndrome are probably deleterious for the kidney." (PMID 37176025, 2023). "Hyperfibrinogenemia occurs due to increased hepatic synthesis in response to glomerular losses of albumin in nephrotic syndrome and has been associated with increased risk of hypercoagulability and thromboembolism." (PMID 35927678, 2022). "Serum albumin levels are often low as well, due to loss of albumin in the urine (usually serum albumin is < 2.5 g/dL in nephrotic syndrome)." (PMID 35754443, 2022). "In contrast, there is a direct loss of albumin during nephrotic syndrome, peritoneal dialysis, and high-flux hemodialysis." (PMID 36262258, 2022).
nephrotic syndrome (continued). "The slightly decreased plasma albumin and clearly increased plasma cholesterol concentrations represented typical alterations that hint towards significant renal protein loss, as seen in nephrotic syndrome." (PMID 35533204, 2022). "Urinary loss of vitamin D bound to its carrier protein (DBP) and to albumin in patients with nephrotic syndrome has been implicated as a main cause for vitamin D deficiency in patients with nephrosis." (PMID 35800433, 2022). "CD2AP has a role in glomerular filtration by maintaining podocyte intercellular junctions, and its deficiency leads to albumin excretion and nephrotic syndrome." (PMID 34356879, 2021). "In the same context, the possibility of diagnostic misinterpretation increases if albumin decreases and globulin increases, such as in nephrotic syndrome." (PMID 32046075, 2020). "In patients with nephrotic syndrome, the heavy urinary loss of thyroid hormone-binding proteins, including thyroxine binding globulin, thransthyretin, and albumin, results in a reduction in total T431." (PMID 29391480, 2018). "Based on this observation, it was concluded that the presence of the nephrotic syndrome and of a low serum albumin (< 2.5 g/l) at presentation was associated with a significantly greater risk of TE." (PMID 22963194, 2012). "The primary abnormality in nephrotic syndrome is increased glomerular permeability, leading to severe albuminuria causing low serum albumin, decreased oncotic pressure, and increased water retention by kidneys due to activation of epithelial sodium channel (ENaC)." (PMID 39131015, 2024). "The primary abnormality in nephrotic syndrome is increased glomerular permeability, leading to severe proteinuria causing low serum albumin, decreased oncotic pressure, and increased water retention by kidneys due to activation of the epithelial sodium channel (ENaC)." (PMID 39131015, 2024). "Medicinal HSA is approved for the substitution treatment of albumin loss, for example systemic capillary leakage or nephrotic syndromes, or general protein loss such as in burn injuries, as well as failure to generate sufficient albumin such as in liver failure." (PMID 33941197, 2021). "Furthermore, podocin (Nphs2) is a critical protein component of podocyte filtration slits, and its deficiency or mutation can cause focal segmental glomerulosclerosis leading to nephrotic syndrome, with massive leakage of albumin into urine." (PMID 32400101, 2020). "Hypoalbuminemia indicated severe loss of albumin as seen in cases with nephrotic syndrome." (PMID 28819567, 2017). "Previously, facets of serum albumin biology and pathobiology have been uncovered indirectly based on hypoalbuminemic states caused by hepatic insufficiencies, nephrotic syndrome, and protein-losing enteropathies and through limited studies of familial human analbuminemias." (PMID 25654695, 2015). "The low serum albumin reflects inflammation, but in the case of nephrotic syndrome in 9 (6%) patients, large renal loss of proteins could affect the simple regression outcome." (PMID 18234104, 2008). "However, care has to be taken in those with underlying conditions that may affect protein and albumin turnover such as nephrotic syndrome, hypothyroidism, and chronic liver disease, where the values may be inaccurate." (PMID 39911238, 2024). "Interestingly, albumin-associated FFAs have been shown to induce macropinocytosis in podocytes and the podocyte response to FFAs has been proposed to function in the development of nephrotic syndrome by amplifying the effects of proteinuria." (PMID 26919698, 2016). "The molecular weight of VDBP is similar to that of albumin and, therefore, it is excreted in urine along with albumin in patients with nephrotic syndrome." (PMID 41259273, 2026). "Protein wasting in nephrotic syndrome can deplete albumin, and drugs or clotting factor consumption can increase INR and prothrombin time." (PMID 41493845, 2026).